REN (renin)
Diseases named in the same sentence as REN in open-access papers (continued):
Sharing a sentence is not in itself a finding about the gene and the disease.
Hypertension (continued). "Acquired AME should be suspected in individuals who present with hypertension along with hypokalemia, metabolic alkalosis and low plasma renin and serum aldosterone levels." (PMID 39107810, 2024). "The relationship between the kidneys and hypertension is complex, involving factors such as the renin–angiotensin system, oxidative stress, and inflammation." (PMID 39513878, 2024). "Adequate treatment of PA can significantly reduce morbidity and mortality by reducing increased aldosterone and relieving renin suppression and hypertension." (PMID 38966219, 2024). "The pathogenesis of hypertension in obesity involves multiple factors, including increased sympathetic nervous system activity, activation of the renin-angiotensin-aldosterone system (RAAS), and renal compression due to fat accumulation." (PMID 39217385, 2024). "Hypertension is characterized by upregulation of the renin–angiotensin system, increased blood–brain barrier (BBB) permeability, microglia activation within autonomic nuclei, and an intense sympathoexcitation." (PMID 39328833, 2024). "Blockers of the renin–angiotensin–aldosterone system (RAAS) is the cornerstone in the treatment of hypertension." (PMID 39795879, 2024). "It helps regulate the renin-angiotensin system (RAS), reducing hypertension, which is a major risk factor for DKD." (PMID 39185464, 2024). "Malaria disrupts the renin-angiotensin-aldosterone system (RAAS), causing higher angiotensin-II and aldosterone levels, contributing to edema, hyponatremia and hypertension." (PMID 39492784, 2024). "Pseudohyperaldosteronism (PHA) is characterized by hypertension, hypokalemia, and a decrease in plasma renin and aldosterone levels." (PMID 39000561, 2024). "The three hallmark signs of PA are a high aldosterone blood level, a suppressed renin level, and hypertension." (PMID 38255973, 2024). "The renin–angiotensin–aldosterone system (RAAS) is frequently used in the treatment of hypertension and to help slow kidney disease progression." (PMID 39768487, 2024). "Hypertension plays a vital role in regulating the renin–angiotensin–aldosterone system (RAAS) and immune responses, leading to the release of cytokines and increased inflammation." (PMID 38398867, 2024). "Approximately one-third of patients with hypertension have essential hypertension and low plasma renin activity (PRA), also known as low-renin hypertension (LRH)." (PMID 38410670, 2024). "The three hallmark signs of PA are high aldosterone blood levels, a low/suppressed renin level, and hypertension." (PMID 38255973, 2024). "The renin–angiotensin–aldosterone system (RAAS) activation is the primary etiologic event in the development of hypertension in subjects with DM." (PMID 39200267, 2024). "Other studies with VDR knockout mice showed stimulation of the renin–angiotensin–aldosterone system favoring hypertension, increased fluid intake, and left ventricular hypertrophy." (PMID 39267468, 2024). "Hypertension is characterized by the stimulation of the renin-angiotensin-aldosterone system (RAAS)." (PMID 38576704, 2024). "Pseudohypoaldosteronism type II (PHA II) or Gordon syndrome is characterized by hyperkalemia, hypertension, hyperchloremic metabolic acidosis, low plasma renin activity, and normal kidney function." (PMID 38374860, 2024). "The potential mechanisms of hypertension, including the renin-angiotensin system and sex hormones, are also influenced by gender." (PMID 39439560, 2024). "This study will explore if a similar cardioprotective effect is seen in low-renin hypertension by titrating spironolactone to both blood pressure and renin concentration." (PMID 39026100, 2024). "Patients with concordant and discordant tests were comparable for baseline characteristics such as gender, age, duration of hypertension, BMI, plasma aldosterone and renin concentration." (PMID 39678193, 2024).
Hypertension (continued). "Experimental studies showed that uric acid was a potent activator of the renin–angiotensin–aldosterone system, contributing to hypertension development." (PMID 38370360, 2024). "Obesity and hypertension share common pathophysiological mechanisms, such as overactivity of the renin–angiotensin–aldosterone and the sympathetic nervous systems, insulin resistance, and disruption of the leptin pathway." (PMID 39457606, 2024). "Lastly, the involvement of PTH in the Renin–Angiotensin–Aldosterone axis highlights the importance of opting for the appropriate pharmacological agent should hypertension develop." (PMID 38785509, 2024). "In two ethnic South African populations, an association was observed between renin–angiotensin–aldosterone system (RAAS)-related genes and the development of hypertension." (PMID 38541065, 2024). "In the mentioned study, authors explore a rolefor variants in SCNN1B, GRK, NEDD4L, NPPA, and UMOD in asmall substudy of 9 patients selected with low renin, low aldosterone concentration, andresistant hypertension in sub-Saharan Africa." (PMID 39281005, 2024). "Included in this list are medications targeting hypertension, such as beta-blocking agents, calcium channel blockers, and agents that act on the renin–angiotensin system." (PMID 38651370, 2024). "PAC and ARR were higher and direct renin concentration was lower in patients with PA than in patients with essential hypertension." (PMID 38536656, 2024). "In fact, esaxerenone at 1.25 to 5.0 mg ×1 secondary increased plasma renin activity and plasma aldosterone concentration in essential hypertension or primary aldosteronism, which is reflective of hypoaldosteronism." (PMID 39090747, 2024). "In contrast, others defined low renin as the lowest tertile of measured renin in a trial population with essential hypertension." (PMID 38200100, 2024). "The origin of essential hypertension remains a puzzle, but extensive discussions have revolved around the involvement of key systems: the renin–angiotensin system, the autonomic nervous system (ANS), body fluid volume and the peripheral vasculature." (PMID 38378540, 2024). "All patients with discordant results showed a mild phenotype of autonomous aldosterone production in the area of overlap between PA and low-renin essential hypertension." (PMID 39126022, 2024). "Juxtaglomerular cell tumor (JCT) is an endocrine tumor marked by elevated renin levels and high blood pressure." (PMID 38304038, 2024). "Hypertension is a characteristic of PE and the renin–angiotensin system is known to play an essential role in its mechanism." (PMID 37226086, 2023). "At the same time, hyperuricemia stimulates the renin–angiotensin system, leading to hypertension and renal vascular constriction, producing a vicious cycle that further exacerbates progression of kidney disease." (PMID 38155948, 2023). "One of these mechanisms is its inhibitory effect on renin biosynthesis, which is involved in the pathogenesis of hypertension." (PMID 36882686, 2023). "The SS rat has a low-renin salt-sensitive form of hypertension—the type of hypertension most prevalent in the African American population." (PMID 37107157, 2023). "Hypertension-induced upregulation of the vasoconstrictor axis of the renin-angiotensin system within autonomic areas is accompanied by either large increase in local angiotensin II availability and important autonomic imbalance." (PMID 36909225, 2023). "Most of them induce hypertension by increasing the renal tubular reabsorption of sodium and are characterized by a suppressed plasma renin concentration or plasma renin activity." (PMID 39712235, 2023). "These alterations include increased insulin resistance, activation of the renin-angiotensin-aldosterone system and arterial hypertension." (PMID 37738256, 2023). "Patients with AME display low birth weight, postnatal failure to thrive, severe juvenile low-renin, the onset of severe hypertension, and hypokalaemia." (PMID 37201134, 2023).
Hypertension (continued). "The median age of the breast cancer group was 53 years (range, 32–74 years), they had a mean body mass index of 30 kg/m2 and minimal cardiovascular comorbidities with only 2 (8%) participants receiving renin-angiotensin inhibitor treatment for hypertension." (PMID 37847761, 2023). "High UA is assumed to be involved in the development of hypertension and renal vasoconstriction via activation of the renin-angiotensin system (RAS) and reducing endothelial nitric oxide bioavailability." (PMID 36979653, 2023). "Renin-angiotensin-aldosterone system (RAAS) inhibitors are well known as effective drugs for the treatment of hypertension and the anti-remodeling of affected organs." (PMID 37842366, 2023). "Excluding these 6 controls with low-renin hypertension, the DRC cut-off of 10 μU/mL at 2 hours after oral furosemide had a sensitivity of 95.3%, specificity of 93.7% and accuracy of 95% for PA diagnosis." (PMID 38075562, 2023). "Hypertension and renin-angiotensin-aldosterone system (RAAS) activation were successfully induced in both HHcy 2K1C and 2K1C mice." (PMID 36907919, 2023). "Among the processes associated with hypertension, angiotensin I-converting enzyme (ACE), which is involved in the kallikrein–kinin system (KKS) and renin–angiotensin system (RAS), plays a pivotal role in the development of hypertension." (PMID 37446242, 2023). "Hypertension (HTN) involves genetic variability in the renin-angiotensin system and characterizing this variability will help advance precision antihypertensive treatments." (PMID 37066278, 2023). "Patients with GRA are characterized by the clinical presentation of early-onset of severe hypertension with the low plasma renin activity (PRA) and mild hypernatremia in which synthetic glucocorticoid administration suppresses this mineralocorticoid excess." (PMID 37201134, 2023). "Connexin-40 (CX40) is abundantly expressed in JGC, and its knockout mice show hypertension due to the inability to inhibit renin secretion; this has been considered one of the candidates for the main body of the baroreceptor." (PMID 36831037, 2023). "Patients with hypertension have relatively higher levels of plasma renin and plasma renin activity (PRA)." (PMID 36836101, 2023). "In terms of hypertension treatment, medicines that act on the renin-angiotensin system (ACEi and ARBs) are currently and have been for most of the study period, regarded as first-line medications for individuals with T2D." (PMID 37310947, 2023). "For patients with pre-existing hypertension, who are on renin-angiotensin system blockers, dose increases or additions of a different drug class should be considered." (PMID 37763669, 2023). "Taken together, these findings identify PRDM6 as a hub for a network of genes that regulate BP and characterize PRDM6 as a critical regulator for renin-dependent hypertension." (PMID 36602864, 2023). "A meta-analysis study has indicated Fok I polymorphism of the VDR gene results in formation of a truncated protein that evidently increases the synthesis of renin and angiotensin II, thereby promoting the development of hypertension." (PMID 36788562, 2023). "Measurement of renin and aldosterone levels coupled with genetic testing is indicated if monogenic hypertension is suspected." (PMID 38187076, 2023). "The effect of hypertension on bones seems to be regulated through the renin angiotensin aldosterone (RAAS) axis." (PMID 38282945, 2023). "Renin–angiotensin–aldosterone system inhibitors (RAASis) are the standard of care for diabetic patients with hypertension and albuminuria." (PMID 38069366, 2023). "Growing evidence has revealed that the renin-angiotensin-aldosterone system (RAAS) is involved in the occurrence of diabetes-induced hypertension." (PMID 36675205, 2023). "The main pathophysiological change of CoA is hypertension proximal to coarctation, and the postulated mechanisms of hypertension are mechanical obstruction and renin-angiotensin-mediated humoral mechanisms." (PMID 37025297, 2023).
Hypertension (continued). "Hypertension is a resultant clinical indicator intricately controlled by the renin-angiotensin-aldosterone system (RAAS)." (PMID 37308552, 2023). "Clinical therapy for CKD is mostly based on the management of hypertension and proteinuria, partially achieved with renin–angiotensin–aldosterone system (RAAS) blockers, and the control of inflammation by immunosuppressive drugs." (PMID 37633958, 2023). "Six out of 22 hypertensive patients in the control group had low-renin hypertension (suppressed DRC and low aldosterone levels after repeated measures)." (PMID 38075562, 2023). "Our study went one step further to show that perinatal use of taurine can protect offspring from hypertension along with restoring the expression of renin, AGT, ACE, and AT1R induced by maternal CKD." (PMID 38136178, 2023). "Sustained hyperglycemia also activates the renin-angiotensin system to form angiotensin II, which is involved in the development of DN and concomitant hypertension." (PMID 37239172, 2023). "Intramedullary injection of butyrate can dramatically lower Ang II-induced hypertension in hypertensive rats by inhibiting the release of renin and angiotensinogen." (PMID 38029244, 2023). "The inhibitors of the renin-angiotensin-aldosterone system prevent diabetes in patients with hypertension." (PMID 37894687, 2023). "PRA can be used to distinguish between volume-dependent hypertension (suppressed renin) and hyper-reninemic hypertension, which can affect hypertension management." (PMID 36409371, 2023). "The AT1 receptor has mainly been associated with the pathological effects of the renin-angiotensin system (RAS) (e.g., hypertension, heart and kidney diseases), and constitutes a major therapeutic target." (PMID 37513355, 2023). "We already know that renal efferent sympathetic activity participates in renin release, sodium retention and reduced renal blood flow, which contribute to the development of hypertension." (PMID 36759871, 2023). "Hypertension, baseline eGFR, and therapy with Renin-angiotensin-aldosterone system inhibitors proved to be significant factors associated with both AKI and AKD." (PMID 37361572, 2023). "LS, also known as pseudohyperaldosteronism, is a rare autosomal dominant inherited disorder clinically manifested by an early onset of hypertension, metabolic alkalosis, hypokalaemia, low renin levels, and suppressed aldosterone production." (PMID 37201134, 2023). "In this study, we observed that blood pressure and serum renin content were increased in patients with diabetes and hypertension." (PMID 36675205, 2023). "Five out of 6 patients with low-renin hypertension remained with DRC <10 μU/mL at the end of the oral furosemide test." (PMID 38075562, 2023). "The process of vascular remodeling, which results in hypertension, consists of complex interactions between multiple systems, including the immune system, the renin–angiotensin system, the vascular system, and the central nervous system." (PMID 37298077, 2023). "We performed a multivariable time-dependent Cox regression analysis adjusting for sex, age, type of insurance, hypertension, renal disease, and use of antiplatelets and renin–angiotensin–aldosterone system inhibitors." (PMID 37951886, 2023). "Liddle syndrome is an autosomal dominant disorder characterized by hypertension, hypokalemia, low aldosterone levels, and reduced renin activity." (PMID 38013303, 2023). "Different targets for regulating hypertension in the body include the renin-angiotensin system, calcium channels, and beta and α1-adrenergic receptors." (PMID 37389408, 2023). "The mechanism of hypertension in kidney disease is related to decreased capacity of the kidney to excrete sodium, hypersecretion of renin, and increased activation of the sympathetic nervous system." (PMID 37138213, 2023).
Hypertension (continued). "The pathophysiological interaction between hypertension and dyslipidemia, which includes oxidative stress, proinflammatory activities, renin–angiotensin–aldosterone system activation, and endothelial dysfunction, has been supported by accumulating evidence." (PMID 37664830, 2023). "One common model of low-renin hypertension involves delivery of deoxycorticosterone acetate (DOCA) and a high dietary sodium load." (PMID 37293629, 2023). "Activation of the renin–angiotensin–aldosterone system is the common pathophysiological basis of hypertension and atrial fibrillation." (PMID 37202743, 2023). "Renin–angiotensin system hyperactivation in autosomal-dominant polycystic kidney disease (ADPKD) patients leads to early hypertension." (PMID 37043156, 2023). "One of the pathogeneses of hypertension is elevated levels of renin, angiotensin, and aldosterone, and so patients with hypertension will experience high renin in their bodies." (PMID 37448666, 2023). "Nearly 70% of hypertension onsets in adults can be attributed to obesity, primarily due to increased sympathetic nervous outflows and the dysregulated renin–angiotensin system." (PMID 36831252, 2023). "A study found that the lack of vitamin D in obese children can increase the secretion of renin and angiotensin II and the abnormal transcription of endothelial nitric oxide synthase (eNOS), resulting in hypertension." (PMID 36839194, 2023). "Commonly prescribed for arterial hypertension, the inhibitors of the renin–angiotensin system have recently been described as having an inhibitory effect on fibroblasts." (PMID 37686288, 2023). "This in turn affects the renin-angiotensin-aldosterone system and overall increases sodium retention and promotes hypertension." (PMID 36979798, 2023). "Inhibition of angiotensin-I converting enzyme (ACE) is an important means of treating hypertension since it plays an important regulatory function in the renin-angiotensin system." (PMID 37761189, 2023). "There have also been case series describing PNETs secreting renin and erythropoietin, resulting in hypertension and polycythemia, respectively." (PMID 37046665, 2023). "One of the common presenting signs of RI is hypertension, which occurs due to ischemia-mediated Renin release." (PMID 37038580, 2023). "The expression of CSE was decreased, and renin content was elevated in the serum of patients with diabetes and hypertension, in the serum of db/db mice, and in the cell culture medium of JG cells under hyperglycaemic and hyperlipidaemic conditions." (PMID 36675205, 2023). "Primary aldosteronism (PA) is a heterogeneous group of disorders characterized by autonomous overproduction of aldosterone from the adrenal glands with subsequent increased sodium reabsorption and potassium excretion, low renin and arterial hypertension." (PMID 35536535, 2023). "Angiotensin II is a key member of the renin-angiotensin system and plays a vital role in hypertension and left ventricular hypertrophy." (PMID 37200096, 2023). "Accumulation of VAT has been frequently found in the renin–angiotensin–aldosterone system (RAAS), free fatty acids, and insulin resistance, which were known risk factors for hypertension and abnormalities in the lipid metabolism." (PMID 37229452, 2023). "More recent studies have demonstrated that low-renin hypertension is more common among the elderly, patients of African ancestry, those with heart or renal failure, and women with preeclampsia." (PMID 37293629, 2023). "Masked hypertension is also a strong independent predictor of left ventricular hypertrophy, possibly due to hyperactivation of the renin–angiotensin–aldosterone system in these patients." (PMID 38139229, 2023). "The high prevalence rates have been attributed to endothelial reactivity, inflammation, oxidative stress, and increased sympathetic and renin-angiotensin-aldosterone system activities, which ultimately lead to increased vascular tone and hypertension." (PMID 37908019, 2023).